CRYM (crystallin mu)
Description:
Catalyzes the NAD(P)H-dependent reduction of imine double bonds of a number of cyclic ketimine substrates, including sulfur-containing cyclic ketimines. Under physiological conditions, it efficiently catalyzes delta(1)- piperideine-2-carboxylate (P2C) and delta(1)-pyrroline-2-carboxylate (Pyr2C) reduction, suggesting a central role in lysine and glutamate metabolism. Additional substrates are delta(2)- thiazoline-2-carboxylate (T2C), 3,4-dehydrothiomorpholine-3-carboxylate (AECK), and (R)-lanthionine ketimine (LK) that is reduced at very low rate compared to other substrates. Also catalyzes the NAD(P)H-dependent reduction of (S)-cystathionine ketimine (CysK) (By similarity).
Synonyms: THBP; DFNA40
Tractability: Small molecule: a structure with a bound ligand is known; it has a high-quality binding pocket. PROTAC: its protein half-life has been measured.
Gene: Protein-coding gene on chromosome 16 (21,238,874 to 21,303,083, reverse strand). Ensembl gene ENSG00000103316.
Subcellular location: Cytoplasm
Subcellular location (Human Protein Atlas): Cytosol
Pathways (Reactome):
Metabolism: Lysine catabolism
Gene Ontology:
Molecular function: delta1-piperideine-2-carboxylate reductase activity; NADP binding; protein binding; protein homodimerization activity; thiomorpholine-carboxylate dehydrogenase activity; thyroid hormone binding; transcription corepressor activity; hormone binding; pyrroline-2-carboxylate reductase activity
Biological process: negative regulation of transcription by RNA polymerase II; sensory perception of sound; thyroid hormone transport; L-lysine catabolic process; thyroid hormone metabolic process; amino acid catabolic process
Cellular component: cytoplasm; cytosol; extracellular exosome; peroxisomal matrix; mitochondrion; nucleus
Genetic constraint (gnomAD): Loss-of-function variants: 17 observed, 30.33 expected, observed/expected ratio (o/e) 0.56, 90% interval 0.38 to 0.84. The upper end of that interval is the gene's LOEUF score, 0.84, which puts it in group 3 of 6, group 1 being the genes least tolerant of losing a copy. Missense variants: 329 observed, 383.94 expected, observed/expected ratio (o/e) 0.86, 90% interval 0.78 to 0.94. Synonymous variants: 149 observed, 147.96 expected, observed/expected ratio (o/e) 1.01, 90% interval 0.88 to 1.15.
Gene-disease validity (ClinGen):
ClinGen rates the evidence that CRYM causes each of these diseases.
nonsyndromic genetic hearing loss (autosomal dominant): Limited. A disease characterized by hearing loss that is not part of a larger syndrome.
Homologues: Orthologues: chimpanzee CRYM (99% identical), macaque CRYM (99% identical), rabbit CRYM (93% identical), dog CRYM (92% identical), guinea pig CRYM (90% identical), mouse Crym (89% identical), rat Crym (88% identical), pig CRYM (86% identical), tropical clawed frog crym (70% identical), zebrafish crym (57% identical), Drosophila melanogaster CG4872 (33% identical).
Diseases named in the same sentence as CRYM in open-access papers:
CRYM is named in the same sentence as 27 diseases in open-access papers, as found by Europe PMC text mining. Sharing a sentence is not in itself a finding about the gene and the disease. The quoted sentences say what the papers report.
prostate carcinoma (5 papers, 2012 to 2023). A carcinoma that arises from epithelial cells of the prostate gland. "High expression of thyroid hormone-binding protein μ-crystallin (CRYM) was associated with low choline uptake in 18F-fluoromethylcholine (FMC) PET/MRT studies of prostate cancer patients, suggesting that CRYM expression may be a potential biomarker for prostate cancer (PCa) diagnosis and prognosis." (PMID 38223684, 2023). "Three datasets, Chandran, Grasso and Yu prostate cancer cohorts, clearly showed that CRYM expression was significantly downregulated in metastases compared to the levels in primary PCa (P < .0001)." (PMID 33034050, 2021). "CRYM is responsible for the development of prostate cancer, but this gene may be identified with the pathogenesis of BRCA." (PMID 31311202, 2019).
Huntington disease (3 papers, 2020 to 2024). Huntington disease (HD) is a rare neurodegenerative disorder of the central nervous system characterized by unwanted choreatic movements, behavioral and psychiatric disturbances and dementia. "It has been reported that CRYM expression in the striatum is reduced in Huntington’s disease (HD) mouse model and overexpression of CRYM reduced mutant Htt-mediated neurotoxicity." (PMID 33685490, 2021). "CRYM (Ketimine‐reductase mu‐crystallin) has been reported as a modulator of huntingtin toxicity to striatal neurons in Huntington's disease." (PMID 32485097, 2020). "In previous studies, downregulation of CRYM mRNA was reported in animal models of neurodegenerative disorders, and CRYM was reported to exert neuroprotective effects in the striatum in a mouse model of Huntington’s disease." (PMID 39164609, 2024).
hearing loss (2 papers, 2012 to 2016). "The importance of elevated intralabyrinthine protein underlying hearing loss is supported by previous studies examining unique perilymphatic proteins that are elevated in CVSs, including μ-Crystallin (CRYM) and low density lipoprotein-related protein 2 (LRP2)." (PMID 23049959, 2012). "In this study, we analyzed six proteins causing progressive hereditary hearing loss, five of which (CX31, CRYM, GRHL2, DFNA5, and ATP6B1) do not recapitulate human symptoms in the mouse model." (PMID 26915689, 2016).
adenoid cystic carcinoma (1 paper, 2021). A malignant tumor arising from the epithelial cells. "Thus, our data indicate that CRYM might be a suitable positive prognostic marker in adenoid cystic carcinoma of the head and neck." (PMID 34945824, 2021).
Alzheimer disease (1 paper, 2025). A progressive, neurodegenerative disease characterized by loss of function and death of nerve cells in several areas of the brain leading to loss of cognitive function such as memory and language. "Recent evidence has shown increased expression of SIGLEC10 and decreased expression of crystallin mu (CRYM) in the blood of Alzheimer’s disease patients, with both genes showing potential as diagnostic biomarkers." (PMID 41471108, 2025).
autoimmune disease (1 paper, 2021). A disorder resulting from loss of function or tissue destruction of an organ or multiple organs, arising from humoral or cellular immune responses of the individual to their own tissue constituents. "In Graves' hyperthyroidism, which is an autoimmune disease five times more abundant in females than in males, anti‐thyroid medication with methimazole results in CRYM mRNA overexpression which suggests an inverse correlation of CRYM with thyroid hormone." (PMID 33034050, 2021).
autosomal dominant non-syndromic deafness (1 paper, 2021). "CRYM encodes a crystallin protein, and its mutations may cause autosomal dominant non-syndromic deafness." (PMID 34454438, 2021).
deafness (1 paper, 2012). An inherited or acquired condition characterized by the complete loss of the ability to hear from one or both ears. "Mutations in nine deafness genes (COCH, KCNQ4, MYO7A, TECTA, CRYM, POU3F4, EYA1, mitochondrial tRNA(Lys) m.8296A>G, mitochondrial tRNA(Ser) m.7445A>G) were not identified in any patients." (PMID 22384008, 2012).
demyelination (1 paper, 2024). "Additionally, we explored the potential protective effects of CRYM and PDIA3 against cuprizone-induced demyelination by synthesizing cell-permeable Tat peptide-fusion proteins (Tat-CRYM and Tat-PDIA3) to facilitate their crossing through the blood–brain barrier." (PMID 39164609, 2024).
head and neck cancer (1 paper, 2021). A primary or metastatic malignant neoplasm affecting the head and neck. "We retrospectively assessed immunohistochemical CRYM expression in 121 head and neck cancer patients." (PMID 34945802, 2021).
kidney damage (1 paper, 2023). "In addition, these 106 potential classifiers/biomarkers between TCMR vs. STA are associated with kidney damage (e.g., ATP1B1, CST3, FAH, GSS, HPX and LYZ), tubule injury (e.g., CRYM, GSS, HAGH, HPX and LYZ) and kidney inflammation (e.g., DCN)." (PMID 36814924, 2023).
meningioma (1 paper, 2017). A generally slow growing tumor attached to the dura mater. "The trends of gene expression profiles of candidates such as EFCAB2, EPS8L1, NOL3, PAIP1 and SNX1 showed elevated expression in meningiomas compared to controls, while CAMK2N1, CRYM and PRPSAP2 showed decreased expression levels in meningiomas compared to the controls." (PMID 28938569, 2017).
Parkinson (1 paper, 2021). "CRYM, TH, and GBA were evaluated, as these genes have been shown to be differentially expressed in Parkinson’s models." (PMID 34358063, 2021).
cancer (3 papers, 2021). A tumor composed of atypical neoplastic, often pleomorphic cells that invade other tissues. "Taken together, our data demonstrate an inhibition of cancer‐associated metabolism profiles upon CRYM overexpression and suggest that CRYM expression could abolish the stimulating metabolic influence of T3 on PCa cells." (PMID 33034050, 2021). "The proteins sodium iodide symporter (NIS), μ-crystallin (CRYM), and thyroid hormone receptor beta (THRB) have been associated with prognosis in various cancer entities." (PMID 34945824, 2021). "Glycine, glutamate, creatine and taurine, which are known to be rapidly taken up by growing cancer cells, were increased by T3 treatment but reduced with CRYM overexpression." (PMID 33034050, 2021). "While NIS and THRB may serve as possible therapeutic targets, the role of CRYM in cancer is still unclear." (PMID 34945824, 2021). "To date, the role of CRYM in cancer has only been studied in prostate cancer." (PMID 34945824, 2021). "IFI27, CRYM, HBD, and IFITM3 in TEPs were positively related to the pan‐cancer stage and essential for diagnosing cancers with a sensitivity of 59.1%, 57.8%, 54.3%, and 60.9%, and a specificity of 90.9%, 89.1%, 72.7%, and 94.5%, respectively." (PMID 33955587, 2021). "In this study, 7 TEPs mRNAs were verified, including RSL24D1, IFI27, CRYM, HBD, IFITM3, FCGR2A, and KLHDC8B, which may be used for cancer detection." (PMID 33955587, 2021). "Seven TEPs mRNAs were discovered in our study: RSL24D1, IFI27, CRYM, HBD, IFITM3, FCGR2A, and KLHDC8B in TEPs, which are mainly enriched in protein binding, extracellular matrix, and metabolic process, and may be used for cancer diagnosis." (PMID 33955587, 2021). "Consequently, we believe alternative TEPs mRNAs, including RSL24D1, IFI27, CRYM, HBD, IFITM3, FCGR2A, and KLHDC8B mRNA, can potentially serve as non‐invasive biomarkers for diagnosing cancers and can even predict the prognosis of pan‐cancer." (PMID 33955587, 2021).
tumor (3 papers, 2019 to 2021). "Previous reports demonstrated that CRYM expression was downregulated in PCa patients who underwent ADT12 and that expression of CRYM was also downregulated in a PCa xenograft tumor model." (PMID 33034050, 2021).
infection (1 paper, 2019). The state of being infected such as from the introduction of a foreign agent such as serum, vaccine, antigenic substance or organism. "Overexpression of HA-tagged CRYM in Huh7-LP cells resulted in a slight but reproducible increase in replication of the subgenomic HCV replicon after 72 h, as well as a notable replication upon infection with the JcR2a reporter virus." (PMID 31905685, 2019).
CRYM also shares sentences with these, for which no sentence is quoted: distal renal tubular acidosis (1 paper); Friedreich ataxia (1); Graves' hyperthyroidism (1); kidney inflammation (1); metastatic cancer (1); metastatic tumor (1); multiple myeloma (1); myopathies (1); prostate tumors (1); schizophrenia (1); thyroid (1).